CD74 (CD74 molecule)
Diseases named in the same sentence as CD74 in open-access papers (continued):
Sharing a sentence is not in itself a finding about the gene and the disease.
tumor (continued). "If such an approach could regulate MIF’s immunosuppressing activity and pro-inflammatory arrangements, this would provide a therapeutic strategy if we only prevent CD74 function in antigen presentation to the immune cells in the tumor milieu." (PMID 33327409, 2020). "In brain metastasis, the STAT3-positive reactive astrocytes not only suppressed the activation of CD8+ T cells, but also promoted the expansion of CD74+ microglial/macrophages, which produces tumor growth promoting factors, thereby benefiting metastatic tumor growth in brain." (PMID 31130637, 2019). "Several studies proposed that the MIF/CD74 signaling pathway is an important regulator in pathological tumor-associated angiogenesis and showed that MIF expression levels correlated with tumor angiogenesis." (PMID 31866994, 2019). "In this way, CD74 has a potential role in anti-tumor immune responses." (PMID 31013837, 2019). "Unraveling the factors determining increased kidney cell expression of CD74 may help to design strategies to protect parenchymal cells from the toxicity of CD74 targeting anti-tumor therapies." (PMID 29924850, 2018). "Whole DNA methylome analysis suggested that CD74 tumor cell expression might be regulated epigenetically via CD74 promoter methylation." (PMID 29490700, 2018). "Therefore these different CD74 functions are contradictory with respect to effects on tumor outcome." (PMID 27058619, 2017). "CD74 expression was associated with poor prognostic markers including patient age, tumor grade, ER status, non-Luminal A subtypes, and with MHCII expression and higher TIL densities, particularly in the Basal-like subgroup." (PMID 27058619, 2017). "MIF and CD74 were expressed in C2 organoids and in the corresponding tumour tissue." (PMID 28114961, 2017). "Dual CD74/MHCII positive status is only positively prognostic in the Basal-like tumor subgroup." (PMID 27058619, 2017). "CD74 expression in tumor cells might therefore be expected to mediate both pro and anti tumor effects attributable to its cytokine signaling and antigen presenting functions." (PMID 27058619, 2017). "We hypothesized that tumors that express CD74 along with MHCII, both key components of the antigen presenting machinery, represent those tumors most susceptible to a productive tumor infiltrating leukocyte (TIL) response and correspondingly good outcomes." (PMID 27058619, 2017). "The close association between combined CD74/MHCII expression on tumor cells and the presence of TIL across the entire cohort suggest that a functional relationship exists with antigen presentation on tumor cells." (PMID 27058619, 2017). "However, overall these observations are consistent with the view that CD74 expression in tumor cells promotes the intratumoral immune response and is associated with a better prognosis." (PMID 27058619, 2017). "These different results highlight the complex role of MIF and its receptor CD74 in tumor growth." (PMID 26883190, 2016). "Cytoplasmic and membranous CD74 was also detected in MSTO tumor cells as well as CD44." (PMID 26883190, 2016). "Cytoplasmic and membranous expression of CD74 was detected in H2052 tumor cells." (PMID 26883190, 2016). "CD74 regulates intracellular trafficking and functions as a chaperone and a cell membrane receptor, modulating B, T, and dendritic cell responses and promoting tumor growth by increasing tumor cell survival or proliferation." (PMID 26441987, 2015). "CD74 expression was evaluated by immunohistochemistry in tumor specimens (cancer, n=59) and compared to that observed in tumor-free breast tissues (tumor-free, n=15)." (PMID 24939415, 2014). "Since MIF activity requires binding to CD74, we also examined human tumor expression of CD74." (PMID 24887129, 2014). "RT-PCR revealed the expression of the D-DT receptor CD74 on both tumor cell lines." (PMID 24406307, 2014).
tumor (continued). "Thus, despite the composition of the tumor bank, tumors with integration in Cd74 shared the common characteristic of being induced by B-lymphomagenic viruses." (PMID 20416035, 2010). "However, enhanced CD74-dependent tumour cell proliferation by autocrine MIF was also measured in MDA-MB-468 cells." (PMID 19602265, 2009). "In summary, CD74+ B cells within TLSs, through their intricate interactions with NK and T cells, likely played indispensable roles in promoting their proliferation, migration, and activation, thereby occupying a pivotal position within the tumor immune microenvironment." (PMID 41111459, 2025). "Thus, CD74 expression in tumor-infiltrating neutrophils could serve as a predictive biomarker for immunotherapy response." (PMID 41254689, 2025). "However, how CD74 bridges the crosstalk among tumor cells and immune cells and its function in clinical therapeutics for HCC remain unknown." (PMID 39118044, 2024). "Therefore, our study suggests that CD74 may impair anti‐tumour activity by interacting with CD8+ T cells and modulating the PI3K‐STAT3‐PD‐L1 signalling pathway." (PMID 39113235, 2024). "IFN-γ signaling is particularly important in tumor infiltration and functions by polarizing tumor-associated macrophages (TAMs) from an M2-immunosuppressive type to an M1-pro-inflammatory type; however, it also reduces the presence of CD4 and CD8 T cells in the TME via MIF/CD74 signaling." (PMID 38732068, 2024). "In addition to its expression in immune cells, CD74 is highly expressed in various tumor cells." (PMID 39474111, 2024). "The findings indicate activation of CD74 may have potential in tumor immunotherapy." (PMID 38582956, 2024). "Single-cell analysis and cell communication indicated that PPP1R16A is predominantly distributed in liver malignant parenchymal cells and may reshape the tumor microenvironment by enhancing macrophage migration inhibitory factor (MIF)/CD74 + CXCR4 signaling pathways." (PMID 39010084, 2024). "Interestingly, heterogeneous staining of CD74 was observed within the same cell line, suggesting different expression levels among the tumor cell populations, which could be related to the different responses to osimertinib in the same cell line." (PMID 39001552, 2024). "Therefore, intrinsic resistance to osimertinib may depend on the presence of these CD74-expressing tumor cells." (PMID 39001552, 2024). "However, cDCs in the PI3K/mTORi+PD‐1i‐treated tumours upregulated expression of genes related to antigen presentation via major histocompatibility complex class II (MHC II) (HLA‐DRB1, HLA‐DQB1, HLA‐DPB1, HLA‐DQB2, CD74) compared with cDCs in tumours treated with PD‐1i, PI3K/mTORi‐ or vehicle." (PMID 38711203, 2024). "Research on the association between the BM of NSCLC and the MIF/CD74 axis is limited, with only a few studies discovering that MIF is a tumor cell-oriented factors involved in crosstalk between tumor cells and astrocytes and is associated with tumor angiogenesis." (PMID 38685050, 2024). "Interestingly, intensive interactions were found between macrophages and malignant cells, with four of the most commonly reported ligand–receptor pairs CD74-MIF, SPP1-CD44, CD74-COPA and CD74-APP, whose dysregulations are associated with tumor initiation and metastasis." (PMID 38827297, 2024). "An indirect co-culture of fibroblasts and tumor cells revealed that fibroblasts exposed to conditioned media from CD74 knockdown cells exhibited a reduced expression of inflammatory cytokines, suggesting a role of CD74 in influencing cytokine secretion in the tumor microenvironment." (PMID 37629174, 2023). "Furthermore, a number of interferon (IFN) response genes (BST2, CD74, HLA-DMA, HLA-DPB1, HLA-DQB1, HLA-DRA, HLA-DRB1, and IRF8) were upregulated in C10 compared to the other clusters, whereas genes associated with tumor suppression and apoptosis (TFF1 and TFF2) were downregulated." (PMID 37370788, 2023).
tumor (continued). "Tumor cell gene expression also changed significantly in mANK-101–treated animals, with increased Stat1, Cxcl9, and Cxl10 (all consistent with IFN-γ signaling), as well as increases in Cd74, MHC alleles, and proteasome components, indicating increased antigen processing and presentation." (PMID 38063196, 2023). "Moreover, scRNA-seq analysis revealed that fibroblast and ductal cells might affect malignant tumor cells via MIF-(CD74+CD44) and SPP1-CD44 axis." (PMID 38095640, 2023). "Therefore, the B16 tumour model and other cold tumours with similar T-cell desertification issues are not likely to naturally respond to ICT and would benefit from combinatorial approaches that block the MIF/CD74 axis to unleash DCs-dependent priming of anti-tumour CD8 + T cells." (PMID 37454231, 2023). "CD74, a key molecule involved in antigen presentation, B-cell differentiation and inflammatory signaling, could be considered as a new candidate target and vaccine for tumor immunotherapy to combat tumors." (PMID 36712973, 2022). "In addition, they noted that PMEL and SPP1 were overexpressed in the tumor cell cluster whereas lymphoid tissue regions far away from and near, the tumor cell areas were characterized by expression of the immune-related genes CD74 and IGLL5, respectively." (PMID 35590346, 2022). "CD74 may facilitate HLA-DR internalisation to trigger stronger immunogenicity against tumours." (PMID 35208514, 2022). "Therefore, CD74 is crucial for the activation of adaptive immunity against tumor cells." (PMID 34572445, 2021). "Low expression levels of the MHC class II transporter and antigen presenting gene CD74 in TAS as compared to tumor of BA vs WA PCa patients may suggest a reduced tumor antigen presentation in TAS in BA patients, as class II MHC processing and regulation cannot properly occur in the absence of CD74." (PMID 34316327, 2021). "In sum, MIF/CD74 co-expression might be the major predictor for tumor growth in CRC." (PMID 33542244, 2021). "However, since CD74 expression may impact anti-tumor immune responses, decreased MHC class II expression may lead to reduced tumor cell immunogenicity." (PMID 34944801, 2021). "The results of GO analysis showed that the DEGs (CD74, PAFAH1B1) were associated with the biological process of the cytokine-mediated signaling pathway, suggesting that these two genes may have the potential to stimulate tumor growth and progression." (PMID 31998788, 2020). "However, in contrast to these numerous convergent findings on the detrimental role of MIF in favouring anti-tumour immune response another study has demonstrated that MIF receptor CD74 expression in human gliomas is restricted to microglia/macrophages and positively associated with patient survival." (PMID 29707160, 2018). "Thus, CD74 appeared to be primarily expressed in malignant mesothelial cells, indicating that such tumor cells may be prone to stimulation with MIF." (PMID 26883190, 2016). "The general lack of correlation between proviral status and expression levels in end-stage tumors could reflect tumor heterogeneity, which is supported by Southern blotting analyses, and/or that consequences of Cd74 deregulation are manifested at a stage earlier on in the progression of the tumors." (PMID 20416035, 2010). "In these types of cancer, CD74 frequently co-localizes with MIF at the tumor-stromal interface, activating downstream signaling pathways that sustain tumor growth and metastasis." (PMID 41597203, 2026). "Tumor suppression of this axis results in immune evasion, thereby linking MHC-II and CD74 expression to cancer." (PMID 41597203, 2026). "A key rationale for incorporating CD74 into vaccine constructs is that Ii naturally directs MHC-II complexes to endosomal and lysosomal compartments, where tumor antigens can be processed and loaded efficiently." (PMID 41597203, 2026).
tumor (continued). "Differential gene expression confirmed elevated levels of MIF, CD74, CD44, and SPP1 in tumor tissues, while pathway enrichment analyses highlighted cytokine signaling, antigen presentation, and chemokine-regulated immune modulation as key biological processes." (PMID 41683916, 2026). "Our experiments showed that CD74 activated the ERK1/2-MAPK signaling pathway by binding to MIF, promoting the proliferation and survival of tumor cells." (PMID 41275376, 2025). "We also found that CD74 promotes the infiltration of macrophages, memory B cells, and CD8+ T cells in the tumor microenvironment." (PMID 40470045, 2025). "Upon binding to (CD74+CD44) complexes, extracellular MIF triggers downstream signaling that exacerbates inflammation, tumor growth, and metastasis." (PMID 40948800, 2025). "We found that the signaling of VEGFA-VEGFR1, VEGFA-VEGFR2, MIF-(CD74 + CXCR4) and MIF-(CD74 + CD44) was significantly increased in the high-risk state; whereas the signaling of LGALS9-CD45, LGALS9-CD44, and IL1B-IL1R2 was decreased, which may affect the tumor cell adhesion and migration." (PMID 40563096, 2025). "B cells attracting NK cells in CD74 CD44 MIF neighborhoods was linked to better survival at 20 μm (log-HR = -1.48, p = 0.033) and 60 μm (log-HR = -1.73, p = 0.0018), indicating that NK cell presence close to B cells in these regions may contribute to an effective anti-tumor response." (PMID 40364843, 2025). "This study aimed to establish a radiomics model to predict CD74 expression level in NSCLC patients and to explore its role in the tumor immune response and its prognostic value." (PMID 40470045, 2025). "However, analysis of single‐cell RNA‐sequencing (RNA‐seq) of GB patient tumors revealed that tumor cells do not express CIITA nor genes encoding for MHC‐II antigen processing (CD74, HLA‐DMA, HLA‐DOA) and presentation (HLA‐DQA1, HLA‐DQB1, HLA‐DRA, HLA‐DRB1, HLA‐DRB5)." (PMID 39535369, 2025). "Canonical markers were used to annotate different cell types: malignant cells (COL1A1, IBSP), myeloid cells (CD74, CD14), osteoclasts (CTSK, MMP9), pericytes (RGS5, ACTA2), endothelial cells (PECAM1, VWF), and tumor-infiltrating lymphocytes (CD3D, NKG7)." (PMID 40730548, 2025). "Among the DEGs, we detected some marker genes (CD74, RAB11FIP1, and CST3) related to tumor invasion which are highly expressed in region C3." (PMID 40639417, 2025). "Ligand–receptor interaction mapping revealed that tumor-derived MIF and macrophage-expressed CD74 (with co-receptor CD44) form a signaling axis in ZDHHC9-high tumors." (PMID 40740766, 2025). "Driving lipid metabolic reprogramming and immunosuppression through MIF-(CD74+CD44)-mediated macrophage polarization, our work finds FOS as a master regulator of the malignant C0 MAFF+ tumor cell subtype in LUAD." (PMID 40936936, 2025). "IHC analysis revealed that CD74 and CXCR4 were highly expressed in the infiltrating immune cells within the tumor tissues." (PMID 40018995, 2025). "In preclinical studies, treatment with Ibudilast decreased CD74 expression and increased CD8+ T cell infiltration within the tumor, suggesting its potential in treating brain malignancies." (PMID 41159021, 2025). "VARGG accurately reveals the spatial organization of tumors and identifies key genes related to tumor progression and immune microenvironment (VEGFA, CD74, SPP1, IGFBP5, TIMP2, EMP1, THY1)." (PMID 41275376, 2025). "In contrast, combining LSD1 inhibition with anti‐PD‐1 therapy effectively halted tumour growth and prevented relapse, likely through TME remodelling, enhanced CD8+ T cell activity and improved CD74‐mediated antigen presentation." (PMID 40356247, 2025). "The interaction that existed between MIF, its receptor CD74, and the chemokine receptor, CXCR4, is crucial in tumor biology, particularly cancer progression and metastasis." (PMID 40066443, 2025).
tumor (continued). "The ligand‐receptor interactions between tumor cells and major immune cell populations were mainly present in the MIF signaling pathway, with the ligand‐receptor pair MIF‐(CD74 + CXCR4) exerting the most significant influence on this pathway." (PMID 40018995, 2025). "CD74, a survival/proliferation mediator via migration inhibitory factor signaling, was >20-fold lower in VSIRKO, potentially disrupting tumor-promoting pathways." (PMID 40580480, 2025). "Importantly, tumor cells from patients with EGFR mutation showed increased expression of several MHC class I and II genes compared to tumor cells from patients with KRAS mutant tumors, along with an increase in CD74, which regulates the presentation of MHC class II proteins." (PMID 39803458, 2025). "Multiplex immunofluorescence further confirmed that HER2+ tumour cells highly expressed MIF and were spatially proximal to CD74+ CD8+ T cells." (PMID 40624675, 2025). "For instance, several studies have found a positive correlation between CD74 and MHC class II molecule expression, leading to a higher overall survival rate in certain tumor patients." (PMID 40470045, 2025). "These tumor subtypes cooperatively drive CD8+ T cell exhaustion through the MDK–(ITGA4+ITGB1), MIF–(CD74+CXCR4), and TGF-β signaling pathways." (PMID 40948762, 2025). "Due to their pivotal roles in modulating the immune response, promoting tumor progression, and facilitating immune evasion across various cancer types, we also focused on soluble CD4 (sCD4), soluble CD73 (sCD73) and soluble CD74 (sCD74)." (PMID 39910579, 2025). "Substantiating this premise, EC4 subclass analysis identified conserved functional modules including ECM remodeling effectors (HSPG2,MGP,POSTN) and tumor niche-modifying factors (RAMP2,ACKR1,CD74)." (PMID 41394809, 2025). "CD74, HGF, and SUB1 are frequently overexpressed in NSCLC, promoting tumor proliferation and survival." (PMID 40136480, 2025). "Recent single-cell transcriptomic analyses have identified a unique subset of anti-tumor neutrophils in the TME marked by high HLA-DR and CD74 expression, enabling antigen presentation." (PMID 41009604, 2025). "Previous studies have shown that when CD74 and CD44 are both present in CRC, the tumor becomes more aggressive." (PMID 40842994, 2025). "Focusing on the SSR4+ and SSR4- cell subtypes, SSR4 expression levels were closely related to the interaction patterns that existed between tumor plasma cells as well as other cell subtypes, especially in the MIF/CD74/CXCR4 pathway." (PMID 40066443, 2025). "Previous studies have shown that blocking CD74-MIF signaling can enhance T cell infiltration and reduce tumor growth." (PMID 40364843, 2025). "For example, neutrophils and NK cells showed significant interactions with tumour cells through pathways such as MIF‐(CD74 + CXCR4) and ANNEXIN‐(FPR1 + FPR2), which are known to modulate immune responses and tumour progression." (PMID 40099956, 2025). "Chemotactic interactions promote attraction and activation of cytotoxic cell subsets, likely promoting anti-tumor activity in the TME of R (pDC GPI → NK AMFR, pDC MIF → NK T CD74/CXCR4, and NK T CCL3L1 → CD8 + T CCR5)." (PMID 41185627, 2025). "In this study, we reported that radiotherapy ameliorated tumor hypoxia, downregulated HIF-1α expression and MIF secretion in NSCLC, and inhibited the binding of MIF to CD74 in microglia." (PMID 38685050, 2024). "MIF, CD74, and CD44 exhibit interplay and mutual regulation mechanisms in tumor development and progression." (PMID 38277205, 2024). "Our findings identify specific subsets of CD74+ tumour cells in LSCC with COPD and preliminarily explore their regulatory mechanisms and roles using CD74‐overexpressing or knockdown cell lines and co‐culture experiments." (PMID 39113235, 2024). "MIF exerts its pro-tumor effects by modulating the immunosuppressive TME, mainly via regulating the CD74 signaling in macrophages and dendritic cells (DCs)." (PMID 38685050, 2024).